TRBV5-3 (T cell receptor beta variable 5-3 (non-functional))
Description:
Probable non-functional open reading frame (ORF) of V region of the variable domain of T cell receptor (TR) beta chain. Non-functional ORF generally cannot participate in the synthesis of a productive T cell receptor (TR) chain due to altered V-(D)-J or switch recombination and/or splicing site (at mRNA level) and/or conserved amino acid change (protein level). Alpha-beta T cell receptors are antigen specific receptors which are essential to the immune response and are present on the cell surface of T lymphocytes. Recognize peptide-major histocompatibility (MH) (pMH) complexes that are displayed by antigen presenting cells (APC), a prerequisite for efficient T cell adaptive immunity against pathogens. Binding of alpha-beta TR to pMH complex initiates TR-CD3 clustering on the cell surface and intracellular activation of LCK that phosphorylates the ITAM motifs of CD3G, CD3D, CD3E and CD247 enabling the recruitment of ZAP70. In turn ZAP70 phosphorylates LAT, which recruits numerous signaling molecules to form the LAT signalosome. The LAT signalosome propagates signal branching to three major signaling pathways, the calcium, the mitogen-activated protein kinase (MAPK) kinase and the nuclear factor NF-kappa-B (NF-kB) pathways, leading to the mobilization of transcription factors that are critical for gene expression and essential for T cell growth and differentiation. The T cell repertoire is generated in the thymus, by V-(D)-J rearrangement. This repertoire is then shaped by intrathymic selection events to generate a peripheral T cell pool of self-MH restricted, non-autoaggressive T cells. Post-thymic interaction of alpha-beta TR with the pMH complexes shapes TR structural and functional avidity.
Synonyms: TRBV53; TCRBV5S3; TCRBV5S5P
Gene: T-cell receptor variable (V) gene on chromosome 7 (142,389,202 to 142,389,668, forward strand). Ensembl gene ENSG00000211715.
Subcellular location: Cell membrane
Gene Ontology:
Biological process: cell surface receptor signaling pathway
Cellular component: plasma membrane
Homologues: Paralogues in human: TRBV5-5 (80% identical), TRBV5-6 (79% identical), TRBV5-1 (77% identical), TRBV5-4 (77% identical), TRBV5-7 (76% identical), TRBV9 (60% identical), TRBV13 (55% identical), TRBV7-6 (46% identical), TRBV7-9 (46% identical), TRBV7-7 (46% identical), TRBV11-2 (45% identical), TRBV11-3 (45% identical), and 39 more.